MYC (MYC proto-oncogene, bHLH transcription factor)
Diseases named in the same sentence as MYC in open-access papers (continued):
Sharing a sentence is not in itself a finding about the gene and the disease.
cancer (continued). "We herein summarize the existing therapeutic opportunities aimed at targeting MYC-driven metabolic pathways for cancer therapy." (PMID 32651356, 2020). "For instance, stauprimide treatment, which suppresses MYC transcription in various cancer cell lines, induces selective down-regulation of MYC target genes including DCTPP1." (PMID 31377845, 2020). "In cancer cells having high MYC expression, MYC accumulates in the promoter regions of active genes and brings about their transcriptional amplification." (PMID 32410663, 2020). "As expected, we find that the target genes of MYC are significantly up-regulated in numerous cancer types—in fact, it has the most up-regulated targets of any TF—consistent with its well-known role as a key oncogenic TF31,32." (PMID 32728046, 2020). "We also found copy number loss of cancer genes such as CCNE1, MAF, MAFB, MYC, ZNF479, and MGMT and copy number gain of FOXA2, CDH10, and GPC5 in at least two WDPM cases." (PMID 32545767, 2020). "The oncogene MYC is a transcription factor that drives cancer cell growth by controlling universal transcription programs, including the cell survival, cell cycle, and metabolism." (PMID 33298911, 2020). "Physiologically, MYC levels must be precisely set to faithfully amplify the transcriptome, but in cancer MYC is quantitatively misregulated." (PMID 33005010, 2020). "ZIC2, as transcription factor (TF), behaved as the other core pluripotent TFs (SOX2, NANOG, c-MYC) in cancer stem cells." (PMID 32922547, 2020). "It has been noted that in cancer cells, cathepsin L is induced by MYC; moreover, cathepsin C is known to be up-regulated by MYC in TAMs." (PMID 33081056, 2020). "Although survival of MYC hyperactivated cancers was not reduced in this dataset, a connection to the basal‐like cancer was again observed, which confirms the documented connection of MYC to this subtype of PDAC." (PMID 33099868, 2020). "MYC can activate tyrosine phosphatase signaling pathways which are important mechanisms involved in signal transduction in cancers." (PMID 33351778, 2020). "MYC-driven cancer cells exhibit enhanced glutamine utilization accompanied by increased expression of key glutaminolysis enzymes, including GLS1/GLS2 and GLUD1178–180." (PMID 32943735, 2020). "Four out of 238 MYC regulated intergenic lncRNAs were highly expressed in nearly all CCLE (Cancer Cell Line Encyclopedia) cell lines and were significantly positively correlated with MYC expression levels." (PMID 33134177, 2020). "Deregulation of MYC activity contributes to cancer progression, metastasis and resistance to therapy." (PMID 33298978, 2020). "AMPK-related kinase 5 shares a synthetic lethal interaction with MYC, as its inhibition leads to ATP reduction and pro-apoptotic response stimulation in cancer cells with MYC overexpression." (PMID 32883316, 2020). "CDCP1 has been shown to promote survival of several different types of cancer cells by activating MYC, AKT, and Wnt gene pathways." (PMID 32817447, 2020). "While MYC plays an important oncogenic role in many cancers, it is challenging to be directly targeted by small molecules and antibodies due to a lack of an enzymatic active site and its nuclear location." (PMID 32164294, 2020). "MYC expressing tumors thus become addicted to and depend on the oncogene, as shown in cancer models with conditional activation of MYC." (PMID 33322239, 2020). "On the contrary, let-7 has target genes [HMGA2 (High Mobility Group AT-Hook 2), IMP-1 (IGF2 mRNA-binding protein 1), LIN28B (Lin-28 homolog B), Ras, and MYC) important for cancer cell stemness." (PMID 32150871, 2020). "Kinase inhibitors targeting the PI3K/AKT/mTOR pathway do not only serve as indirect MYC inhibitors, but also directly target cancer metabolism." (PMID 33092116, 2020).
cancer (continued). "Analysis of CNVs in the top-10 HCC cancer-related genes with focal CNVs showed a larger number of amplifications in MYC (4q12) in low AR-RNA patients (FDR = 0.07)." (PMID 33328560, 2020). "Deregulated expression of MYC promotes proliferation and growth of cancer cells, and alters intermediary metabolism to match the enhanced demand for anabolic metabolites." (PMID 32651356, 2020). "The MYC oncogene is a transcription factor that is one of the most commonly activated oncogenes in the pathogenesis of many types of human cancer including HCC." (PMID 31933479, 2020). "This technology was applied to quantify a cancer biomarker, c-MYC, but it can be further extended to any other disease biomarker." (PMID 32183359, 2020). "What is more, it is shown that MYC also promote the expression of MMP9, VEGF, HIF-1α, and TGF-β (all genes associated with cancer aggressiveness) in TAM." (PMID 33081056, 2020). "The proto-oncogene MYC is overexpressed in the vast majority of human cancers and thus has been the focus of intense research interest for some time." (PMID 31102668, 2020). "Meanwhile, unrestrained growth in response to oncogenic MYC expression creates dependency on MYC-driven metabolic pathways, which in principle provides novel targets for development of effective cancer therapeutics." (PMID 32651356, 2020). "SLC7A5 has been extensively studied in a variety of cancers and it is regulated by the oncogene c-MYC." (PMID 32200487, 2020). "8q24.21 is a fragile region on chromosome 8, which is amplified in many types of cancer and harbors the MYC proto-oncogene." (PMID 33329688, 2020). "We also discuss the potential of targeting key UPR signaling nodes as novel synthetic lethal strategies in MYC‐driven cancers." (PMID 32310340, 2020). "In a similar vein, super-enhancers control human MYC transcription via CTCF in the context of high-MYC cancers." (PMID 32527935, 2020). "MYC plays a significant role in many human cancers by regulating several cellular processes including cell proliferation, cell differentiation, metabolism, apoptosis, angiogenesis, and genomic stability." (PMID 33134177, 2020). "Even small increases in MYC abundance are sufficient to promote proliferative cell growth; thus, understanding the molecular control of MYC expression can provide crucial insight into the mechanisms of MYC dysregulation in cancer." (PMID 32527935, 2020). "In neuroblastoma, MYC was shown to upregulate the levels of glutaminase 2, which in turn sustains viability and proliferation of cancer cells." (PMID 32932943, 2020). "The ability of MYC to drive protein synthesis is essential for cancer proliferation and can be inhibited at different levels from ribosome production to protein translation." (PMID 31973211, 2020). "SEs were found to be associated with various oncogenic molecules including both c-MYC and MYCN; this makes them putative therapeutic targets for cancer therapy." (PMID 33628735, 2020). "Since most MYC-driven cancers, including BL, remain addicted to this oncogene, MYC inhibition appears to be an attractive therapeutic strategy." (PMID 32138178, 2020). "In principle, MYC increases the expression of genes involved in cell growth and proliferation, survival of cancer cells and regulation of cellular metabolism." (PMID 32878211, 2020). "MYC’s strong correlation to cell proliferation is well known and blocking the cell cycle of rapidly dividing cancer cells is a reasonable strategy deployed for treatment of cancer." (PMID 33585252, 2020). "First, in 9502 patients with 33 different types of human cancer, the subset of tumors with MYC and TWIST1 predicts poor survival, CCL2/IL13 expression and TAM infiltration." (PMID 31933479, 2020). "With such a high percentage of the genome under the control of MYC, it is unsurprising that this protein has a central role in tumorigenesis across many cancer types." (PMID 33182685, 2020).
cancer (continued). "In cancer, the activity of the MYC transcriptional network is frequently deregulated, contributing to the initiation and maintenance of disease." (PMID 32895364, 2020). "The Pearson correlation coefficient for SWI/SNF subunit genes with MYC in each cancer types is tabulated in the table." (PMID 31932624, 2020). "In support, MILIP expression levels correlated with MYC gene expression in diverse human cancer types." (PMID 33020477, 2020). "Efforts to dissect functions of MYC have frequently relied on cancer models in which MYC levels rise up to 20-fold, in contrast to 1–2 fold physiological elevation of MYC expression in PCa." (PMID 32681068, 2020). "Using this system, it has been demonstrated that exposure of macrophages to cancer cells conditioned medium induced the expression of MYC, as well as alternative activation markers including ALOX15, CD209, and MRC1." (PMID 33081056, 2020). "BET inhibitors OTX015 and JQ1 have been reported to induce c-MYC down-regulation in several cancer types including TNBC." (PMID 32218352, 2020). "c-MYC (MYC) encodes a transcription factor and was one of the first oncogenes to be discovered in human cancers." (PMID 31638140, 2020). "The ratio of ENO1/MBP1 expression in cancer cells is regulated by glucose, with c-MYC-driven elevated ENO1 expression under high glucose conditions, and elevated MBP1 expression under low glucose conditions." (PMID 33584813, 2020). "Among the oncogenes activated by lactate is MYC, a potent mediator of tumorigenesis whose deregulation has been found in a variety of cancers." (PMID 33153193, 2020). "MYC is arguably the best characterized proto-oncogene that is aberrantly activated in ~40% of human cancers by chromosomal translocation, gene amplification, and by upstream oncogenic signals." (PMID 33020477, 2020). "The transcription factor MYC, commonly amplified in cancers, induces the expression of several splicing factors, and subsequently contributes to altered splicing." (PMID 32481522, 2020). "Although both MYCN and MYC upregulation occurs in the childhood cancer neuroblastoma, elevated MYCN is the strongest predictor of a poor prognosis." (PMID 33092025, 2020). "Among these MYC members, c-MYC is perhaps the most frequently dysregulated protein in human tumorigenesis, thereby serving as a promising therapeutic target for cancer treatments." (PMID 32754274, 2020). "Signatures for MYC activity and proliferation were positively correlated in all cancers with the vast majority showing strong positive correlations (r > 0.5)." (PMID 32681068, 2020). "A comprehensive list of metabolic alterations in specific cancer types driven by MYC has recently been reviewed." (PMID 32292719, 2020). "MYC is a very prominent oncogene, and is deregulated in many cancers, leading to worsening prognoses due to its involvement in cell proliferation pathways." (PMID 32138149, 2020). "PVT1 is elevated in MM and coamplified with MYC in many cancers; there is an association between PVT1 expression level and poor prognosis in many cancers." (PMID 32992461, 2020). "Given the importance of MYC for human cancers, we discuss the implications that these interactions have for new therapeutic strategies against human blood cancers." (PMID 33134177, 2020). "The reprogrammed growth, proliferation, and metabolism driven by oncogenic MYC render cancer cells more vulnerable to the disruption of certain biological processes on which they rely." (PMID 32310340, 2020). "For example, MAPK-driven oncogenesis induced mitochondrial fission, while MYC-driven cancer promoted a fused morphology." (PMID 32503622, 2020). "Plasmacytoma variant translocation 1 (PVT1) is a highly conserved lncRNA, which is located downstream of MYC gene and is frequently co-amplified with MYC in several cancer types." (PMID 32154165, 2020).
cancer (continued). "The ubiquity of MYC deregulation in cancer makes it an attractive therapeutic target with broad clinical potential." (PMID 32651356, 2020). "Our results also showed that the expression of cancer stem cell marker genes (e.g., MYC, NANOG, OCT4, and KLF4) was higher in C4-2B cells than that in LNCaP cells and it was markedly decreased by the silencing of SETD1A." (PMID 32629770, 2020). "STAT3, JAK1, and MYC are three oncogenes that have both anti-apoptotic and proliferative effects on cancer cells." (PMID 33391626, 2020). "Recently, FAM83H was reported to have roles in cancer progression in conjunction with oncogenic molecules such as MYC and b-catenin." (PMID 32460791, 2020). "Studies in cancer suggest that targeting the MYC/PP2A network is an achievable strategy for the clinic." (PMID 32110991, 2020). "Later on, the interplay between SRC and MYC has been described in several other cancers, such as melanoma, non-Hodgkin lymphoma, osteosarcoma, and lung cancer." (PMID 32545574, 2020). "Previous studies have paid great attentions to cancer-related genes, e.g. hTERT, c-MYC, BLC2, KRAS, and VEGF, which contain enriched G4 motifs in their promoter regions." (PMID 32257105, 2020). "Similar to the situation in MYC-driven cancer cells, glutamine uptake is enhanced in K-Ras-driven cells via upregulation of SLC1A5181." (PMID 32943735, 2020). "Going forward, continued efforts to discern the molecular mechanisms by which MYC mediates oncogenic effects in different lymphocyte lineages promise to yield even more insights into how this potent oncogene can drive cancer in zebrafish, and in humans." (PMID 32341750, 2020). "The majority of functional studies have focused on c-MYC due to its broad expression profile in human cancers." (PMID 33628735, 2020). "SOX2 and OCT4, along with other induced pluripotent stem cell markers KLF4, NANOG, and c-MYC, regulate stemness in CSCs and have been used them to characterize CSCs in other cancer types." (PMID 33147716, 2020). "A four step procedure was implemented to generate a cancer-centric GRN oriented towards the MYC oncogene." (PMID 32843692, 2020). "Concerning the high MYC expression rate of multiple malignant tumors, elucidating the mechanism controlling the transcriptional activity of MYC is a crucial issue because it will lead to therapeutic targets." (PMID 32411526, 2020). "Targeting ribosome biogenesis has been proposed as a therapeutic strategy for hematological malignancies, ovarian, prostate, and MYC-driven cancers." (PMID 31285544, 2020). "LAT1 plays a major role in the transport of neutral essential amino acids, including methionine, and is driven by several cancer-related genes such as MYC." (PMID 32811569, 2020). "We also see CTNNB1, KLF4, HIF1A, and MYC as particularly important across many cancers as well as evidence to suggest substantial cross-talk and perhaps overlap." (PMID 33106165, 2020). "In contrast, disturbed cell cycle progression upon MYC depletion is variable, primarily leading to the enrichment of cancer cells in the S or G2/M phases." (PMID 32761127, 2020). "The pleiotropic roles of MYC in regulation of cancer cell metabolism have promoted evaluation of inhibiting metabolism, as selective therapeutic opportunities." (PMID 32651356, 2020). "Hyperactivation of MYC occurs in 60–70% of all human cancers, and MYC is classified as a major cancer driver." (PMID 31944520, 2020). "On the other hand, oncogene and cancer related genes, such as MYC, FOS, JUN, and growth promoting genes were upregulated in U1 AMO, but downregulated in U1 OE." (PMID 31911652, 2020). "One strategy exploited by cancer cells to escape from the differentiation program involves the upregulation of the MYC oncogene." (PMID 32722129, 2020).
cancer (continued). "These include well-known cancer-associated genes, such as CCND1 (25 tumors), CDK4 (25 tumors), MDM2 (23 tumors), SETDB1 (23 tumors), ERBB3 (11 tumors), ERBB2 (11 tumors), MYC (10 tumors) and MYCN (five tumors)." (PMID 32025003, 2020). "A large portion of human cancers is characterized by mutations in genes encoding SWI/SNF subunits; furthermore, some oncogenes like MYC and KRAS can interact with SWI/SNF subunits promoting cancer progression in leukemia, lung and colon cancer cells." (PMID 33339101, 2020). "Because of its significant role in regulating different characteristics of cancer cells to promote tumorigenesis, MYC activity is tightly regulated through intracellular PPIs." (PMID 31638140, 2020). "Together, MYC and Twist1 induce the cancer cell to secrete cytokines like Ccl2 and Il13 that lead to recruitment and polarization of macrophages respectively, thus causing metastasis." (PMID 31933479, 2020). "A compounding observation was that the actual transcription rate of MYC was paradoxically lower in the cancer cells than in normal cells to question the importance of the oncogenic super-enhancer in MYC transcription." (PMID 32158925, 2020). "Phang's group has emphasized the metabolic link between glutamine and proline controlled by c-MYC in human cancers." (PMID 33117704, 2020). "RNA silencing and pharmacologic inhibitors were used to evaluate the functions of CDK7/p38α/MYC/PD-L1 axis in cancer cell proliferation and antiPD-1 therapy resistance." (PMID 32690037, 2020). "Pan-cancer analyses of at least 12 cancer types estimated the frequency of MYC amplification at ~14%56–58." (PMID 32895364, 2020). "Accordingly, a myristoylated peptide representing the BASP1 ED interferes with the growth of v‐Myc‐transformed cells and of human cancer cell lines containing elevated MYC levels." (PMID 31944520, 2020). "In cancer cells having high MYC expression, MYC brings about transcriptional amplification of all active genes apart from the induction of its target genes." (PMID 32410663, 2020). "MYC, in turn, can blunt the production of ROS triggered by mTORC1, thus curbing ROS overload in cancer cells." (PMID 31819197, 2020). "In models of Ras- or MYC-driven cancer, signalling through these oncogenes has been shown to lead to sensitivity to ATR inhibition." (PMID 32354033, 2020). "Aberrant MYC activity and overexpression leads to genome-wide dysregulation driving classic cancer hallmarks of proliferative signaling, altered cellular energetics and angiogenesis." (PMID 33182685, 2020). "Although multiple studies have focused on identifying the transcriptional regulation network that drives MYC expression in cancer, little efforts are invested into studying the posttranslational regulation." (PMID 33208877, 2020). "This specificity provides a compelling rationale for PIN1-dependent therapeutic strategies to treat MYC-dependent cancers." (PMID 32300594, 2020). "As MYC TFs are frequently upregulated in cancer but have proven difficult to target directly, blocking MYC expression and/or targeting the transcription machinery downstream of MYC, by inhibiting CDK7, is an attractive strategy." (PMID 32385714, 2020). "Although MYC orchestrates a broad range of biological functions, it has been shown in many cancers that MYC drives tumorigenesis by potentiating or stimulating cell growth and proliferation." (PMID 32681068, 2020). "This is further substantiated by the fact that normal cells have lower levels of Sp1 and c-MYC than cancer cells." (PMID 33329574, 2020). "The association of these proteins with DEK-NUP214 was proposed to promote activation of several cancer associated pathways, such as AKT/mTOR, Src family kinase (SFK), ABL1, and c-MYC pathways." (PMID 32664447, 2020). "We further extended the analysis to one of the MYC proficient cancer cell models, Medulloblastoma where we observed differential expression of most of the SWI/SNF subunits with significant adj.P-values." (PMID 31932624, 2020).